GDNF (glial cell derived neurotrophic factor)
Diseases named in the same sentence as GDNF in open-access papers (continued):
Sharing a sentence is not in itself a finding about the gene and the disease.
diverticular disease (5 papers, 2013 to 2023). A complex disorder characterised by mucosal outpouchings (diverticulae) of the colonic wall which can become infected and inflamed leading to diverticulitis, perforation and bleeding. "Samples of tunica muscularis (TM) and laser-microdissected myenteric ganglia from patients with diverticulosis, DD and controls were analyzed for mRNA expression levels of GDNF, GFRA1, and RET by RT-qPCR." (PMID 28152033, 2017). "As diverticular disease (DD) is associated with reduced myenteric neurons, alterations of the GDNF system were studied in asymptomatic diverticulosis (diverticulosis) and DD." (PMID 28152033, 2017). "Analysis of the tunica muscularis revealed that GDNF mRNA expression was significantly down-regulated in both patients with diverticulosis (62% ± 10% of control values) and DD (55% ± 7% of control values)." (PMID 28152033, 2017). "Furthermore GFRA1 and RET myenteric plexus mRNA expression of patients with diverticulosis and DD was down-regulated, whereas GDNF remained unaltered." (PMID 28152033, 2017). "Although no morphometric alterations of the ENS was found in patients with symptomless diverticulosis, decreased mRNA expression of GDNF and mRNA expression and fluorescence-intensity of its corresponding receptors GFRα1 and RET were found not only in DD but also in asymptomatic diverticulosis." (PMID 28152033, 2017). "We therefore raised the question whether the GDNF system might be altered in earlier stages of diverticular disease formation." (PMID 28152033, 2017). "In addition, we found both receptors and its ligand GDNF down-regulated in the tunica muscularis of patients with asymptomatic diverticulosis and this result was confirmed by site-specific gene expression experiments using RNA extracts from the myenteric plexus." (PMID 28152033, 2017). "Although no myenteric morphometric alterations were found in patients with diverticulosis, GDNF, GFRA1 and RET mRNA expression was down-regulated in the TM of patients with diverticulosis as well as DD." (PMID 28152033, 2017). "Since enteric muscle layers and neuronal tissue vary in mRNA expression levels of GDNF and its corresponding receptors, we performed site-specific mRNA expression analysis of RET, GFRA1 and GDNF of RNA isolated from myenteric ganglia of patients with diverticulosis and DD." (PMID 28152033, 2017). "Thus, we performed a consensus-based morphometric analysis of the myenteric plexus and investigated the expression levels of GDNF and its receptors GFRα1 and RET in the tunica muscularis and myenteric plexus of patients with diverticulosis, DD, and controls at gene and protein level." (PMID 28152033, 2017). "However, both morphometric analysis with respect to consensus-based recommendations of colonic innervation disorders and alteration of GDNF and GDNF receptor mRNA expression were only investigated in patients with DD and data from patients with asymptomatic diverticulosis are still lacking." (PMID 28152033, 2017). "However, we demonstrated, that the down-regulation of components of the GDNF system already occurs in earlier stages of this illness, namely in asymptomatic diverticulosis, where no inflammatory events could be observed before." (PMID 28152033, 2017).
Dyskinesia (5 papers, 2016 to 2025). A movement disorder which consists of effects including diminished voluntary movements and the presence of involuntary movements. "Studies have indicated that GDNF treatment can restore some clinical symptoms in Parkinsonian monkeys and improve dyskinesia in PD patients." (PMID 39741957, 2024). "TEAEs that occurred more frequently in the GDNF group than in the placebo group (difference of ≥3 patients between treatment groups) included dyskinesia, paraesthesia, Lhermitte’s sign, ON and OFF phenomena, and diplopia." (PMID 30808022, 2019). "In the present study, we found a mild decrease of GDNF in 6-OHDA-lesioned ipsilateral substantia nigra in dyskinesia group." (PMID 27613848, 2016). "The level of GDNF was obviously elevated in 6-OHDA-lesioned ipsilateral substantia nigra of rTMS group compared with dyskinesia group (P < 0.05)." (PMID 27613848, 2016). "Taken together, our data clearly indicated that rTMS may benefit for the treatment of dyskinesia in PD through rescuing the degenerative dopaminergic neurons and avoiding the fluctuations of striatal dopamine level via promoting the GDNF expression." (PMID 27613848, 2016). "GDNF-related adverse events included dyskinesia and ON/OFF phenomena, but without the problematic diphasic dyskinesias reported in a previous foetal graft trial." (PMID 30808022, 2019).
gastric cancer (5 papers, 2017 to 2024). A primary or metastatic malignant neoplasm involving the stomach. "Tumor-associated macrophage-derived GDNF facilitates gastric cancer liver metastasis via GFRA1-mediated autophagy flux." (PMID 38962317, 2024). "The study found that six genes (MINT25, RORA, GDNF, ADAM23, PRDM5, MLF1) presented differential methylation between gastric cancer and normal mucosa in the training and test population." (PMID 32489454, 2020).
Insulin resistance (5 papers, 2020 to 2025). Increased resistance towards insulin, that is, diminished effectiveness of insulin in reducing blood glucose levels. "GDNF, CNTF, BDNF, and NRG4 improve insulin resistance and alleviate hepatic steatosis by reducing hepatic lipogenesis and improving β-oxidation." (PMID 32175323, 2020). "In particular, STZ-induced insulin resistance in astrocytes reduces endogenous neurotrophic factor expression, including GDNF, and disrupts the IR/IRS-1/Akt signaling pathway, which is part of the downstream cascade activated by GDNF through RET." (PMID 40456763, 2025).
neuropathy (5 papers, 2016 to 2025). A disorder affecting the nervous system that manifests with pain, tingling, numbness, and/or muscle weakness. "Despite this, we showed that the expression especially of NGF, NGFR, NTRK1, GFRA1, GFAP, and GDNF was upregulated in patients with severe neuropathy as compared to healthy subjects and diabetic patients with subclinical neuropathy." (PMID 30648113, 2018). "Extrapolating, reduced surface expression of GDNFR‐α due to a PIG gene defect could render GDNF ineffective and result in a peripheral (and central) neuropathy." (PMID 39444079, 2025). "In this context, decreased binding of neurogenic transcription factors to the mutated enhancer in dog could explain the weak expression of GDNF/GDNF-AS partnership in neuropathies." (PMID 28033318, 2016). "The most important increase noticed in the OSS+CCI group at day 49, when the respective animals were hypersensitive to the cold plate, seems to indicate that GDNF could have an additional stress-related function that could be more pronounced than the neuropathy-related effects per se." (PMID 28536509, 2017). "Alternatively, the role of glial‐cell‐line‐derived neural growth factor (GDNF) as a survival factor for central and peripheral neurons could be considered for IGD‐related neuropathy." (PMID 39444079, 2025). "This work in canine spontaneous forms of human neuropathies allowed the identification of a novel gene GDNF and its regulation mechanism, not yet described in human HSAN, opening the field of clinical trials to benefit both canine and human medicine." (PMID 28033318, 2016).
asthma (4 papers, 2015 to 2026). "GDNF is a growth factor important for neuronal development, and expression in the lung is increased in asthma rat models." (PMID 39739031, 2025). "Here, we investigate the role of glial cell-line derived neurotrophic factor (GDNF) and rearranged during transfection (RET) signaling in PNEC hyperplasia and its therapeutic potential in asthma." (PMID 41968620, 2026).
astrocytoma (4 papers, 2010 to 2022). "Both selective serotonin reuptake inhibitors (fluoxetine and paroxetine) and tricyclic and tetracyclic antidepressants, but not haloperidol and diazepam, stimulated the expression and secretion of GDNF by rat astrocytoma cells C6." (PMID 35563389, 2022). "Brefelamide at 1–100 μM dose-dependently suppresses cell growth in human astrocytoma 1321N1 cells in vitro through reduced glial cell line-derived neurotrophic factor (GDNF) receptor expression, reduced GDNF secretion and reduced phosphorylation of Erk, Akt and c-Jun N-terminal kinases." (PMID 30583484, 2018). "In the culture of the rat astrocytoma C6, which shows significant similarity with primary rat astrocytes at late passages, dexamethasone reduced the expression of VEGF and IGF-1, and the production of GDNF." (PMID 35563389, 2022). "TCGA database analysis also revealed significantly increased GDNF expression in astrocytoma but no significant change in oligodendroglioma (data not shown)." (PMID 32183903, 2020).
dementia (4 papers, 2015 to 2023). Loss of intellectual abilities interfering with an individual's social and occupational functions. "Interestingly, the upregulation of endogenous GDNF in GDNF hypermorphic mice (Gdnfwt/hyper) suppressed a gradual decline in cholinergic transmission, which is one of the hallmarks of dementia." (PMID 36983803, 2023). "To test our hypothesis, herein we analyzed human plasma EVs and NTF (CysC, PGRN, BDNF, and GDNF) in dementia patients (AD, DLB, and FTD diagnoses), investigating also the link between NTF and EVs." (PMID 34046409, 2021). "These cases suggest that SORL1 mutations might result in aggregation of a-synuclein through altered function of GDNF and further lead to appearance of core dementia with Lewy bodies features." (PMID 33879716, 2021). "To this aim, we chose four candidates that were previously demonstrated to be altered in dementias: BDNF, PGRN, CysC, and GDNF." (PMID 34046409, 2021).
lung carcinoma (4 papers, 2010 to 2021). "The GDNF gene was mutated in seven lung cancer samples and one benign disease sample." (PMID 33200540, 2021). "Overexpression of GDNF was also reported to be involved in tumorigenesis of human lung cancer." (PMID 20422010, 2010). "Besides no record about SCN8A, THPA confirmed a similar tendency for an increased expression of HDAC1, DLG1, EPHB2 and CALB1, while GDNF was not apparently changed in either normal or lung cancer tissues; no data were available for SCN8A." (PMID 32102656, 2020).
malignant glioma (4 papers, 2012 to 2023). A grade III or grade IV glioma arising from the central nervous system. "This study not only reveals the mechanism underlying the promotion of C6 cell proliferation after exogenous GDNF administration but also provides a new biological target for the treatment of malignant glioma." (PMID 37594930, 2023). "Since then, it has also been reported that GDNF is highly expressed in malignant glioma tissues and cell lines such as C6, U87 and U251." (PMID 37594930, 2023). "Consistently, exogenous GDNF significantly promoted U251 malignant glioma cell migration and invasion." (PMID 28212546, 2017). "GDNF is approximately five times highly expressed in human malignant gliomas compared to normal human brain tissues." (PMID 28212546, 2017). "GDNF confers chemoresistance in a ligand-specific fashion in malignant gliomas." (PMID 35311096, 2022). "To extend our findings we performed wound healing and transwell invasion assays to determine whether exogenous GDNF affects the migration and invasion of U251 malignant glioma cells." (PMID 28212546, 2017).
migraine (4 papers, 2005 to 2024). "While we are unaware of any data linking GDNF with migraine, increased cerebrospinal fluid levels of NGF are associated with chronic headache." (PMID 15667652, 2005). "Previous studies have shown that migraines are closely related to various neurotransmitters, including adenosine triphosphate (ATP) and glial cell-derived neurotrophic factor (GDNF)." (PMID 37450927, 2024). "GDNF has been directly administered into the CNS, but adverse effects, such as migraine and the presence of antibodies directed against GDNF, have halted further investigation." (PMID 28878618, 2017). "Therefore, the GDNF-TrkB signaling pathway may improve migraine TNC and trigeminal ganglion inflammatory conditions." (PMID 37450927, 2024). "A GWAS in Taiwanese Han Chinese identified two novel migraine susceptibility SNPs: rs655484 in DLG2, a gene involved in glutamatergic neurotransmission; and rs3781545 in GFRA1, which encodes a receptor for glial cell line-derived neurotrophic factor (GDNF) in trigeminal neurons." (PMID 31226929, 2019). "A fuller understanding of the impact of NGF, GDNF and BDNF on TG neurochemical properties has the potential to lead to novel therapeutic strategies concerning disease states involving neuropeptide secretion in the trigeminal system, such as migraine." (PMID 15667652, 2005).
myocardial infarction (4 papers, 2012 to 2019). Gross necrosis of the myocardium, as a result of interruption of the blood supply to the area, as in coronary thrombosis. "It is still not clear whether these unfortunate events are deal to the infusion of GDNF or some other causes including heart attack." (PMID 23251488, 2012). "This is contradicted, however, by findings in a single patient in an early open-label phase I study who was treated with GDNF for 43 months via a unilateral continuous intraputamenal infusion and died from myocardial infarction after the study." (PMID 30808022, 2019). "In contrast, in a mouse model of myocardial infarction and subsequent sympathetic nerve sprouting, myocardial gene expression of GDNF (estimated by RT-PCR)) was, unlike NGF, virtually unchanged." (PMID 23843937, 2013).
osteosarcoma (4 papers, 2017 to 2025). A usually aggressive malignant bone-forming mesenchymal neoplasm, predominantly affecting adolescents and young adults. "Taken together, NGF-TrkA, BDNF-TrkB and GDNF–RET circuits endow osteosarcoma cells with proliferative, anti-apoptotic and pro-metastatic properties." (PMID 41142827, 2025). "Our results showed a previously undescribed drug resistance mechanism in which GDNF-mediated RET phosphorylation at Y1062 promotes osteosarcoma progression by stimulating downstream AKT and ERK pathways." (PMID 31534554, 2019). "NGF–TrkA shows highest expression; BDNF–TrkB and GDNF–GFRα/RET are variable, whereas NT−3/TrkC is low in osteosarcoma but prominent in other bone sarcomas, hence our emphasis." (PMID 41142827, 2025). "Indeed, aberrant GDNF or GFRA1 expression has been often found in various cancer cells including those of the pancreas, skin and breast, as well is in osteosarcoma." (PMID 29617307, 2018). "In addition, RET, a coreceptor of GDNF, was not expressed in osteosarcoma cells." (PMID 29617307, 2018).
pancreatic ductal adenocarcinoma (4 papers, 2021 to 2025). An infiltrating adenocarcinoma that arises from the epithelial cells of the pancreas. "Akt can also be upregulated by CD74 and potentiate the secretion of GDNF to promote the PNI process in pancreatic ductal adenocarcinoma." (PMID 38525111, 2024).
retinal diseases (4 papers, 2010 to 2023). "Looking forward, the GDNF-GFP overexpressing cNPCs developed here are suitable for allogeneic transplantation to the vitreous cavity or subretinal space of cats with retinal disease." (PMID 20936061, 2011). "Glial cell line-derived neurotrophic factor (GDNF) is neuroprotective of retinal neurons, and transduced retinal progenitor cells (RPCs) can deliver this cytokine for the treatment of retinal diseases, yet the potential effects of GDNF on RPCs have received little attention." (PMID 21203407, 2010).
retinitis pigmentosa (4 papers, 2011 to 2022). Retinitis pigmentosa (RP) is an inherited retinal dystrophy leading to progressive loss of the photoreceptors and retinal pigment epithelium and resulting in blindness usually after several decades. "Recent studies have reported that long-term expression of GDNF in photoreceptors or retinal pigment epithelial cells using the tet/on inducible expression system slowed photoreceptor degeneration in rd10 mice, a mouse model of retinitis pigmentosa." (PMID 27657046, 2016).
sarcopenia (4 papers, 2021 to 2025). Progressive decline in muscle mass due to aging which results in decreased functional capacity of muscles. "Our primary finding was the longitudinal correlation of circulating CAF22, BDNF, and GDNF with sarcopenia indexes during the disease course of COPD." (PMID 34575696, 2021). "We applied logistic regression coefficients to the circulating CAF22, BDNF, and GDNF levels to generate predicted probabilities of individual biomarkers for clinical sarcopenia." (PMID 34575696, 2021). "During aging and the development of sarcopenia, significant changes occur in GDNF expression." (PMID 41303670, 2025). "Thus, the reduced upregulation of BDNF and GDNF in the elderly can potentially contribute to sarcopenia in COPD." (PMID 34575696, 2021). "Altogether, measurements of plasma CAF22, BDNF, and GDNF may be helpful for the accurate diagnosis of sarcopenia and functional capacity in COPD during PR." (PMID 34575696, 2021). "We evaluated the circulating biomarkers of NMJ degradation, including c-terminal agrin fragment -22 (CAF22), brain-derived neurotrophic factor (BDNF), and glial cell line-derived neurotrophic factor (GDNF) as predictors of sarcopenia in COPD during pulmonary rehabilitation (PR)." (PMID 34575696, 2021). "Biomarkers such as C-terminal agrin fragment-22 (CAF22), brain-derived neurotrophic factor (BDNF), and glial cell line-derived neurotrophic factor (GDNF) have been identified as predictors of sarcopenia and may guide pharmacologic strategies during pulmonary rehabilitation." (PMID 41450343, 2025). "This protective effect is lost in sarcopenia as circulating BDNF, and GDNF levels decrease in advancing age in both genders." (PMID 34575696, 2021). "The current study aims to address this gap by evaluating circulating BDNF, GDNF, and CAF22 levels as potential biomarkers of sarcopenia in COPD." (PMID 34575696, 2021). "In patients with neurodegenerative diseases, low GDNF levels correlate with signs of sarcopenia and partially normalize after rehabilitation, underscoring its significance as a potential biomarker." (PMID 41303670, 2025).
substance abuse (4 papers, 2011 to 2025). The use of a drug for a reason other than which it was intended or in a manner or in quantities other than directed. "Epigenetic alterations in GDNF expression could underlie both reactivity to stress and vulnerability to substance abuse, leading to health-risk behaviors." (PMID 27445722, 2016). "Recent studies have indicated that the activation of the GDNF pathway has the effect of diminishing both biochemical and behavioral alterations in rats that have been subjected to substance abuse." (PMID 40371361, 2025).
ulcerative colitis (4 papers, 2011 to 2017). An inflammatory bowel disease involving the mucosal surface of the large intestine and rectum. "The expression of GFAP and GDNF in the mucosal plexus is highly increased in the inflamed colon of patients with ulcerative colitis (UC) and infectious colitis." (PMID 21235736, 2011).
Ureteral obstruction (4 papers, 2020). Obstruction of the flow of urine through the ureter. "The renoprotective effects of AD-MSC exosomes overexpressing glial cell line-derived neurotrophic factor (GDNF) was investigated on renal injury using a ureteral obstruction murine model." (PMID 33246476, 2020).